DPP4 (dipeptidyl peptidase 4)
Diseases named in the same sentence as DPP4 in open-access papers (continued):
Sharing a sentence is not in itself a finding about the gene and the disease.
Hyperglycemia (continued). "So, this finding is in keeping with our hypothesis and previous findings that DPP4 inhibition is more likely to alter extracellular mediators such as TGFß1 but not the intracellular regulation induced by hyperglycaemia." (PMID 26509887, 2015). "Therefore, chronic hyperglycaemia induced a significant increase in DPP-4 activity in type 2 diabetic patients with poor metabolic control, probably contributing to the reduction in circulating active GLP-1 and subsequently to postprandial hyperglycaemia." (PMID 21747834, 2011). "However, a recent study showed that DPP-4 inhibitors failed to decrease the progression of kidney damage despite reducing hyperglycaemia and renal DPP-4 activity in a murine model of DKD, suggesting that controlling hyperglycaemia alone is not sufficient for DKD prevention." (PMID 39526061, 2024). "However, 2 mg/kg of linagliptin treatment in KKAy mice for 48 days failed to decrease hyperglycemia although it could sufficiently block DPP4 activity." (PMID 28659588, 2017). "For example, in the treatment of hyperglycaemia, glucagon‐like peptide‐1 receptor agonists (GLP‐1RA) have been shown to reduce cardiovascular events and mortality, while dipeptidyl peptidase 4 (DPP4) inhibitors have not shown the same benefits." (PMID 39888728, 2025). "Moreover, plasma DPP-4 activity is not lowered when glycaemic control is improved in patients with T2DM, thereby also suggesting that hyperglycaemia is not a direct determinant of levels of DPP-4 activity." (PMID 30828317, 2019).
heart failure (185 papers, 2009 to 2026). Inability of the heart to pump blood at an adequate rate to meet tissue metabolic requirements. "In 2016, the FDA issued a warning against two DPP-4 inhibitors (saxagliptin and alogliptin) regarding their role in increasing the risk of serious heart failure events." (PMID 40141772, 2025). "Previous real-world database studies have concluded that SGLT2 inhibitors are superior to DPP-4 inhibitors in reducing the risk of major adverse cardiac or cerebrovascular events, especially heart failure events." (PMID 41041642, 2025). "The findings reported in this article indicate that DPP-4 inhibitors have a neutral impact on all-cause mortality, major cardiovascular events, myocardial infarction, heart failure, and stroke." (PMID 40832578, 2025). "Molecular and biochemical effects of GLP-1 RA and DPP-4 inhibitor treatments influencing cardiovascular health in the research models associated with myocardial infarction (MI) and heart failure." (PMID 40725024, 2025). "These variations underscore the importance of selecting specific DPP-4 inhibitors in heart failure patients based on their cardiovascular risk profile." (PMID 39768866, 2024). "Studies of the effects of DPP-4 inhibitors on LV diastolic function and risk of hospitalization due to heart failure have yielded mixed results and vary between drugs." (PMID 38500750, 2024). "This raised important questions about the safety of DPP-4 inhibitors in patients at risk for or with existing heart failure." (PMID 39768866, 2024). "Studies by Packer (2018) also show a positive correlation between DPP-4 inhibitor use and adverse cardiac events, citing their ability to cause and/or worsen heart failure." (PMID 39080769, 2024). "For example, one clinical study showed that among patients with diabetes and heart failure, SGLT2i was associated with reduced risk of heart failure hospitalization, myocardial infarction, and stroke compared to DPP4 inhibitors." (PMID 39176133, 2024). "A recent study comparing various antidiabetic medications found that dipeptidylpeptidase-4 (DPP-4) inhibitors pose a greater risk of heart failure compared toother drug classes." (PMID 39742220, 2024). "Mechanistic Studies: Further studies are needed to elucidate the molecular mechanisms by which certain DPP-4 inhibitors influence heart failure risk." (PMID 39768866, 2024). "For instance, metformin can cause indigestion, diarrhea, and heartburn, while Dipeptidyl peptidase-4 (DPP-4) inhibitors can increase the risk of heart failure." (PMID 39698026, 2023). "Another study linked the use of DPP-4 inhibitors to an increased rate of heart failure by showing that DPP-4 inhibitors activate the renin-angiotensin-aldosterone system (RAAS), which is involved in maintaining vascular tension and remodeling of the heart." (PMID 37920618, 2023). "Variation in substrate selectivity between different DPP4 inhibitors has been postulated as the underlying mechanism of variance in heart failure risk associated with various agents." (PMID 34097240, 2022). "Hazard ratios for the association between DPP-4 inhibitor use and primary composite outcome, acute myocardial infraction, stroke, and heart failure compared to Sulfonylureas and metformin." (PMID 33057387, 2020). "Another study showed that the use of dipeptidyl peptidase-4 inhibitors were associated with a reduced risk of heart failure hospitalization compared to GLP-1RAs." (PMID 32334592, 2020). "According to another large-scale clinical study, incretin-based therapy by GLP-1 agonists or DPP-4 inhibitors showed a trend for decreased risk of hospitalization for heart failure (1,499,650 patients, with 29,741 hospitalized for heart failure)." (PMID 31341533, 2019). "In summary, DPP4 inhibitors cause 0.5–0.7% decrease in HbA1c and are a well-tolerated option with a neutral cardiovascular profile, except for increased heart failure incidence with saxagliptin." (PMID 31766545, 2019).
heart failure (continued). "After concerns raised by the findings of SAVOR-TIMI 53, several studies have investigated the effect of DPP-4 inhibitors on the risk of heart failure in patients with T2DM." (PMID 30876392, 2019). "Trials involving DPP4 inhibitors have shown a neutral effect on cardiovascular risk, with one trial finding an increased risk of heart failure." (PMID 31766545, 2019). "Accumulating evidence indicates that increased circulating DPP-4 activity is associated with poorer CV outcomes in experimental and clinical heart failure models." (PMID 29669555, 2018). "The result was opposite to previous systematic reviews and meta analyses, among which increased risk of heart failure was found in the treatment of saxagliptin individually or DPP-4 inhibitors as an integrity." (PMID 29787616, 2018). "Some oral anti-hyperglycemic drugs, including gliptins that inhibit dipeptidyl peptidase 4 (DPP4), have been linked to the increased risk of heart failure (HF) in type-2 diabetic patients." (PMID 30487758, 2018). "By comparison, the DPP-4 inhibitors, saxagliptin and alogliptin, carry a regulatory warning about the finding of an increased risk of hospitalization for heart failure in treated patients enrolled in large-scale trials carried out with these drugs." (PMID 29310647, 2018). "In the SAVOR-TIMI trial, the risk of heart failure (HF) was increased by 27% in T2D patients randomized to the dipeptidyl peptidase-4 inhibitor (DPP4i) saxagliptin." (PMID 29549573, 2018). "Despite the reported cardioprotective effect of DPP-4 inhibitors from pre-clinical trials, concerns emerged regarding their potential association with heart failure (HF)." (PMID 30016946, 2018). "The DPP-4 inhibitors are safe in terms of hard cardiovascular endpoints, but their effect on the risk of heart failure remains uncertain." (PMID 28148253, 2017). "DPP4 inhibitor treatments associated with lower risks of mortality as well as MI and ischemic stroke in diabetic patients with pre-existing heart failures." (PMID 28587613, 2017). "A systematic review and meta-analysis on DPP-4 inhibitors found a suggestion of increased heart failure risk, primarily driven by SAVOR, EXAMINE, and VIVIDD trials." (PMID 29270438, 2017). "Despite these limitations, our results demonstrate the cardioprotective effect of DPP-4 inhibitor therapy in the setting of heart failure associated with systemic metabolic dysfunction." (PMID 28771625, 2017). "Results from meta-analyses of randomized trials also demonstrated that DPP-4 inhibitors were associated with an increased risk of heart failure." (PMID 28490337, 2017). "In some studies, DPP-4 inhibitor therapy slightly increased the risk of heart failure, while other studies (including recent large-scale clinical trials) have found no additional risk." (PMID 28771625, 2017). "In the propensity score-matched cohorts, we observed a lower adjusted risk of heart failure hospitalization among patients taking SGLT2 inhibitors than those taking DPP4 inhibitors." (PMID 28756774, 2017). "In 2014, the US Food and Drug Administration raised concerns regarding heart failure risk with one dipeptidyl peptidase-4 (DPP-4) inhibitor, saxagliptin." (PMID 27169565, 2016). "These concerns followed publication of studies that reported increased risk of hospitalization for heart failure in patients using DPP-4 inhibitors." (PMID 27169565, 2016). "The association between DPP4 inhibition and increased risk of heart failure is also supported by another meta-analysis by Monami in 2014." (PMID 26075284, 2015). "We used abdominal aortic banding (AAB) to induce pressure overload in wild-type and DPP4-deficient rats, and investigated the progression of heart failure." (PMID 24416433, 2014).
heart failure (continued). "Across multiple subgroups, GLP-1 RA use was consistently associated with reduced risks of hospitalization for coronary artery disease, stroke, heart failure, end-stage kidney disease, sight-threatening retinopathy, and all-cause mortality compared with DPP-4 inhibitor use." (PMID 41011236, 2025). "Saxagliptin’s potential to cause fluid retention and heart failure exacerbations may be attributed to its unique pharmacokinetics, which lead to greater inhibition of DPP-4 compared to other agents." (PMID 39768866, 2024). "For instance, the SAVOR-TIMI 53 trial raised concerns when it observed an increased risk of heart failure hospitalizations associated with the DPP-4 inhibitor saxagliptin, though other studies with different DPP-4 inhibitors, like sitagliptin, found no such association." (PMID 39768866, 2024). "By inhibiting DPP-4, there is potential modulation of these additional pathways, which could variably impact heart failure depending on the patient’s underlying disease state and the specific DPP-4 inhibitor used." (PMID 39768866, 2024). "However, the observed differences within the DPP-4 inhibitor class, especially regarding heart failure risk, emphasize the importance of individualized treatment decisions." (PMID 39768866, 2024). "We explore the physiological mechanisms by which DPP-4 inhibitors may influence heart failure risk, including modulation of inflammation, oxidative stress, and myocardial fibrosis." (PMID 39768866, 2024). "The variability in cardiovascular outcomes across DPP-4 inhibitors suggests that specific agents may differ in their effects on heart failure risk." (PMID 39768866, 2024). "Furthermore, saxagliptin (one of dipeptidyl peptidase-4 inhibitors) was associated increased risk of heart failure admission in post-hoc analysis of SAVOR-TIMI 53 trial." (PMID 36805666, 2023). "FDA completed cardiovascular outcomes trials for all four US-approved DPP-4 inhibitors and it was found that all DPP-4 inhibitors possess a neutral impact on microvascular and macrovascular events except saxagliptin, which might elevate the heart failure risk." (PMID 37287751, 2023). "However, the use of some DPP-4 inhibitors increased the risk of heart failure and worsened the evolution of heart failure in diabetic patients." (PMID 36834796, 2023). "However, recent studies have revealed certain major side effects of DPP4 inhibitors, including a significant increase in the risk of heart failure, death, myocardial infarction, stroke, and a cumulative gout incidence of 5.25%." (PMID 36769291, 2023). "We believe that the DPP4 enzyme could exert a compensatory function against the altered neuropeptide tone caused by the elevated sympathetic activity in heart failure." (PMID 35884882, 2022). "In various observational studies seemed that sulfonylurea therapy may be related to increased risk of heart failure events compared with dipeptidyl peptidase-4 (DPP-4) inhibitors or metformin." (PMID 34205870, 2021). "However, some studies proved that DPP4 inhibitors increase the risk of hospital admission for heart failure in those patients with existing risk factors of cardiovascular system or cardiovascular diseases when compared with the control group." (PMID 34489872, 2021). "Furthermore, various CVD outcome trials have indicated that DPP-4 inhibitors increase the risk of hospitalizations due to heart failure." (PMID 33530982, 2021). "Furthermore, heart failure is the 1 CV outcome for which glucose-lowering drugs, depending on type, have been shown to both increase risk (thiazolidinediones, the dipeptidyl peptidase-4 inhibitor saxagliptin) and decrease risk (SGLT2 inhibitors)." (PMID 32485734, 2020). "Is it possible that SDF-1 potentiation might explain the increased risk of heart failure reported in trials of DPP-4 inhibitors?" (PMID 29310647, 2018).
heart failure (continued). "Several studies have found cardioprotective effects of incretin-based therapies; however, it remains unclear whether there is any difference in heart failure (HF) risk between the two incretin-based therapies (DPP-4 inhibitors and GLP-1 receptor agonists)." (PMID 30016946, 2018). "Most studies of DPP-4 inhibitors have shown a neutral effect on heart failure risk." (PMID 28903775, 2017). "Amid those uncertainties, the Food and Drug Administration has warned that two DPP4 inhibitors, saxagliptin and alogliptin, may increase the risk of heart failure, especially in patients who already have cardiovascular or kidney disease." (PMID 28756774, 2017). "In this real-world analysis of T2DM patients, our findings suggest that SGLT2 inhibitors are associated with lower risk of heart failure hospitalization than DPP4 inhibitors, specifically among patients older than 65 years of age or those with a prior history of diabetic complications." (PMID 28756774, 2017). "Despite abundant preclinical evidence of cardiovascular benefits of DPP-4 inhibitors, including results presented herein, meta-analyses of clinical data raise concerns regarding evidence of increased risk of heart failure with administration of certain DPP-4 inhibitors." (PMID 27391040, 2016). "Regarding MI and heart failure, pre-clinical studies have demonstrated that DPP4-deficient rats subjected to 45 min of ischemia with 2 h or reperfusion exhibited cardioprotection illustrated by reduced infarct size, improved cardiac performance, and reduced levels of BNP compared to control rats." (PMID 26284071, 2015). "However, DPP4i should be used with caution in T2DM patients with increased vulnerability to DPP4 inhibition-associated heart failure, especially with saxagliptin such as history of heart failure or chronic kidney disease." (PMID 26075284, 2015). "The capability of regulating calcium homeostasis by DPP4 deficiency may be partly contributed to the cardiac function improvement during heart failure." (PMID 24416433, 2014). "In this study, the cardioprotective effect of DPP4 deficiency during heart failure may be involved in more than GLP-1 signaling." (PMID 24416433, 2014). "However, a meta-analysis suggested that saxagliptin may be associated with an increased risk of heart failure-related hospitalizations, while another analysis found an increased risk of atrial fibrillation (RR = 1.52) associated with DPP-4 inhibitors." (PMID 41018201, 2025). "Overall, while DPP-4 inhibitors are generally considered neutral for atherosclerotic CV outcomes, caution is warranted in prescribing saxagliptin - and potentially alogliptin - particularly in patients with pre-existing heart failure or at high risk of developing it." (PMID 41246652, 2025). "Future research could investigate the physiological basis for heart failure risks associated with DPP-4 inhibitors and explore how these medications interact with other antidiabetic agents, such as SGLT2 inhibitors, which have shown positive effects on heart failure outcomes." (PMID 39768866, 2024). "Moreover, subsequent studies are needed to determine whether combination therapies, such as pairing DPP-4 inhibitors with other agents like SGLT2 inhibitors (which have shown favorable outcomes in heart failure), could offset the heart failure risk." (PMID 39768866, 2024). "However, a recent survey of data from Medicare beneficiaries, older than 65 years of which 55% had baseline CVD, did not demonstrate increased risk of stroke, myocardial infarction or heart failure when comparing DPP-4 inhibitors with sulfonylureas (SU) or thiazolidinediones (TZDs)." (PMID 29669555, 2018). "In light of the limited beneficial evidence on SGLT2 inhibitors and potential risk concerns with some of the DPP4 inhibitors, we undertook this study to examine how these two newer drug classes compare with each other in terms of associated risk of hospitalization for heart failure." (PMID 28756774, 2017).